LINC02185 (long independently transcribed non-coding RNA 2185)
Gene: Long non-coding RNA gene on chromosome 16 (13,995,606 to 14,016,109, reverse strand). Ensembl gene ENSG00000262097.
Gene Ontology:
Biological process: SRP-dependent cotranslational protein targeting to membrane, signal sequence recognition
Cellular component: signal recognition particle, endoplasmic reticulum targeting